WEE1 (WEE1 G2 checkpoint kinase)
Diseases named in the same sentence as WEE1 in open-access papers (continued):
Sharing a sentence is not in itself a finding about the gene and the disease.
pancreatic cancer (48 papers, 2010 to 2026). "Mechanistically, the anticancer effects of pevonedistat on pancreatic cancer cells caused the accumulation of the cell cycle-related regulators Wee1, p27, and p21 and finally induced axis-mediated cell cycle arrest and apoptosis." (PMID 35155257, 2022). "Moreover, the WEE1 inhibitor adavosertib associated with gemcitabine showed clinical activity in HR-proficient pancreatic cancer." (PMID 40124650, 2025). "Most recently, we found that MLN4924 could act as a novel radiosensitizing agent by causing accumulation of CDT1 and WEE1 to enhance radiation-induced DNA damage, aneuploidy, G2/M arrest and apoptosis in pancreatic cancer cells." (PMID 22457814, 2012). "The observations of this study suggest that low SORBS1 expression in PANC-1 cells increases WEE1 activity, contributing to DNA damage repair and facilitating pancreatic cancer cell cycle reinitiation, thus conferring resistance to PPH." (PMID 40918460, 2025). "Abrogation of the G2 checkpoint as a potential mechanism of radiosensitization in pancreatic cancer cells has also been shown in vitro and in vivo through controlling translational regulation of WEE1 and RAD51 by metformin." (PMID 36313934, 2023). "Up-regulation of WEE1 after treatment of pancreatic cancer cells with DNA damaging chemotherapy leads to treatment resistance." (PMID 36975505, 2023). "Accordingly, WEE1 inhibition has shown promising results in ovarian and pancreatic cancers, which have high basal levels of replication stress." (PMID 36632060, 2023). "WEE1 is the key kinase and the direct target of CHK1, and its expression is enhanced by KRAS mutation, as shown in pancreatic cancer cells." (PMID 36313934, 2023). "WEE1 inhibitor adavosertib (AZD1775) synergizes with ATM inhibitor AZD0156 in reducing proliferation of pancreatic cancer cells." (PMID 36975505, 2023). "Inhibition of WEE1 has synergistic effects with ATM inhibitors in pancreatic cancer preclinical models in vitro and in vivo." (PMID 36975505, 2023). "We found that neddylation suppression by pevonedistat alone significantly inhibited pancreatic cancer malignant phenotypes by inducing G2 phase cell cycle arrest and Wee1/p27/p21 axis-directing apoptosis." (PMID 35155257, 2022). "Based on the mechanisms by which pevonedistat induced intrinsic cell growth suppression and apoptosis in pancreatic cancer cells, we highlighted the important roles of Wee1, p27, and p21 in this process." (PMID 35155257, 2022). "In preclinical work, Wee1 inhibition sensitizes HR-proficient pancreatic cancer to chemotherapy and radiation." (PMID 34572943, 2021). "The combination of PARP/Wee1 inhibition was previously tested in lung and pancreatic cancer cells with similarities but also some differences to our findings in HPV-positive HNSCC cells." (PMID 34354944, 2021). "In pancreatic cancer cells, MLN4924 caused accumulation of CDT1, WEE1, and NOXA, in parallel with an enhancement of radiation-induced DNA damage, aneuploidy, G2 arrest and apoptosis." (PMID 27224919, 2016). "To further demonstrate the utility of the PLK1 NanoBRET assay, we profiled adavosertib (MK-1775/AZD1775), a WEE1 kinase inhibitor in clinical development for the treatment of pancreatic cancer, whose kinase selectivity has been the subject of debate in the literature." (PMID 37049713, 2023). "First promising clinical results of the combination of Wee1 inhibition and irradiation have already been achieved in a phase 1 clinical trial combining adavosertib with radiotherapy and gemcitabine in pancreatic cancer in line with a previous preclinical study." (PMID 36709315, 2023).
pancreatic cancer (continued). "In pancreatic cancer cells, as a representative KRAS-mutated tumor entity, targeting WEE1 induced sensitization to radiation with a DER of 1.3 ± 0.1 in MiaPaCa-2 cells and gemcitabine chemoradiation in vitro and in vivo through inhibition of the HR repair pathway and abrogation of the G2 checkpoint." (PMID 36313934, 2023). "In addition, three other pancreatic cancer cells treated with pevonedistat also showed similar upregulation of Wee1, p27, and p21." (PMID 35155257, 2022). "In this study, we observed that neddylation inhibition by pevonedistat contributed to G2 phase defects and subsequent cell apoptosis in pancreatic cancer cells by suppressing the ubiquitination and degradation of Wee1, p27, and p21 and inducing their accumulation." (PMID 35155257, 2022). "Wee1 inhibition by adavosertib has been shown to reduce p-CDK1 (Tyr15) levels in pancreatic tumors." (PMID 34298699, 2021). "In pancreatic cancer, preclinical models suggest a combinational approach of a WEE1 inhibitor with radio- and chemotherapy, and a phase I/II trial treated 34 patients with locally advanced PDAC with the WEE1 inhibitor adavosertib (AZD1775) in combination with gemcitabine and radiation therapy." (PMID 34707985, 2021). "However, another study investigating pancreatic cancer cells revealed that the inhibition of WEE1/ATM could effectively down-regulate the expression of PD-L1 by blocking GSK-3β and reducing the expression of CMTM6." (PMID 36071479, 2022). "Furthermore, Wee1 inhibition reduced Cdk1 phosphorylation in patients and shows significant potential as a radio-sensitizing strategy in combination with gemcitabine for the treatment of patients with locally advanced pancreatic cancer." (PMID 34572943, 2021). "To date, the data of only one study have been published combining the WEE1 inhibitor AZD1775 with gemcitabine and RT in pancreatic cancers." (PMID 36313934, 2023). "Co-inhibition of WEE1 combined with ATM reduced the expression of MMP-9, IL-8, CXCL1, CCL2, and CCL5, thus achieving an anti-migration effect in pancreatic cancer (PC)." (PMID 36071479, 2022). "It has been found that the pharmacological inhibition of WEE1 and CHK1 sensitizes pancreatic cancers to gemcitabine." (PMID 31569425, 2019). "A Wee-1 inhibitor, AZD1775, also attenuated Rad51 nuclear localization in pancreatic cancer cells, and resulted in sensitization to DNA damaging effects from radiation and PARPi." (PMID 29340034, 2017). "As additional controls, the indicated pancreatic cancer cells were treated with ABT-888, a poly(ADP-ribose) polymerase 1 and 2 (PARP1/2) inhibitor, or MK-1775, a Wee1 kinase inhibitor and then exposed to IR." (PMID 25344910, 2014). "Unlike what were observed in pancreatic cancer cells, the MLN4924-radiation combination did not further increase the levels of CDT1 and WEE1, but did caused a further increase of p21 in both SK-BR-3 and MCF7 cells." (PMID 22457814, 2012). "Several of the discovered WEE1 inhibitors are of clinical grade and a few are in early-phase clinical development, although, currently, few trials have been specific for pancreatic cancer patients and no trials have used molecular markers of DNA damage for patient selection." (PMID 36975505, 2023). "WEE1 inhibitors may also be synergistic with nucleoside analogue chemotherapy drugs, such as gemcitabine, by reducing the ATR and CHK1 activation induced by gemcitabine exposure of pancreatic cancer cells." (PMID 36975505, 2023). "For example, in a pancreatic cancer preclinical model, the same doses of AZD1775 that were used in the present experiments also did not change the Wee1 expression while showing the effect of radiosensitizer by reducing pCdk117." (PMID 31659268, 2019).
colorectal cancer (46 papers, 2011 to 2026). A primary or metastatic malignant neoplasm that affects the colon or rectum. "In this study, we investigated the association between WEE1 expression and clinicopathological features of colorectal cancer (CRC) using surgical specimens." (PMID 39335109, 2024). "Analysis of WEE1 immunohistochemical expression in 102 colorectal carcinoma patients revealed high WEE1 expression to be associated with both poor OS (P = 0.018) and poor DFS (P = 0.039)." (PMID 33224881, 2020). "Further efforts are needed in both preclinical and clinical settings to exploit DDR alterations as therapeutic targets and to eventually discover PARP or other DDR inhibitors (e.g., Wee1) with clinical benefit on colorectal cancer patients." (PMID 35326540, 2022). "A more recent study showed that DDX56 can induce intron retention of WEE1, a cell cycle-related gene, in colorectal cancer cell." (PMID 34446021, 2021). "A recent study has verified that DDX56 cell promotes proliferation in colorectal cancer through alternative splicing tumor suppressor WEE1." (PMID 32671031, 2020). "The analysis of WEE1 mRNA expression in 43 cases of colorectal carcinomas showed significantly higher WEE1 mRNA expression in tumor tissue compared to adjacent healthy tissue, and high WEE1 mRNA expression was significantly associated with high tumor stage." (PMID 33224881, 2020). "First, we checked the cell viability of combination therapy groups in Wee1 knockdown colorectal cancer cells, contrasted to wild type cells, combination treatment showed limited effect than monotherapy groups in Wee1 knockdown cells." (PMID 31523195, 2019). "Wee1 overexpression has been reported to protect endothelial cells of colorectal cancer from liver metastases and suppress invasion and migration in GC cells." (PMID 29977914, 2018). "In conclusion the data suggest the importance of WEE1 as an enabler of branching vascularisation in colorectal cancer liver metastases." (PMID 28178688, 2017). "Our in vitro data on the positive effects of combinatorial treatment with overexpression of Wip1, Wee1 inhibition and chemotherapy are reinforced by the bioinformatics analyses of patients with colorectal cancer." (PMID 27077811, 2016). "However, the effects of WEE1 inhibitors on the tumor immune microenvironment in colorectal cancer (CRC) remain unclear." (PMID 39335109, 2024). "One such TCGA screen of candidate genes in colorectal cancer identified that loss of DDX56 reduced intron retention and tumor suppressor WEE1 expression, which functions as a G2-M DNA damage checkpoint, postulating that DDX56 could serve as a potential prognostic biomarker of colorectal cancer." (PMID 34680866, 2021). "In this review, we provide an overview of mechanisms, preclinical studies and advances in clinical trials of DNA-PKcs, ATM/ATR, CHK1/CHK2, WEE1 and PARP1 kinase inhibitors combined with radiotherapy for colorectal cancer treatment." (PMID 36230796, 2022). "Recent studies have shown that KIAA1429 promotes colorectal cancer progression by inhibiting WEE1 expression in an m6A nondependent manner." (PMID 38089085, 2022). "Therefore, we provided relevant data that AZD5153 inhibited the expression of Wee1 and impaired the G2M checkpoint, thus sensitized the anticancer effect of BMN673 in colorectal cancer cells." (PMID 31523195, 2019).
hepatocellular carcinoma (40 papers, 2011 to 2026). A malignant tumor that arises from hepatocytes. "Solid tumors, including hepatocellular carcinoma and colon cancer, exhibit elevated expression of WEE1 and PKMYT1." (PMID 40893386, 2025). "This DUBTAC, formed by the WEE1 inhibitor AZD1775 and the OTUB1 recruiter EN523, led to a stabilization of WEE1 similar to that observed upon treatment with the proteasome inhibitor bortezomib in the hepatoma cell line HEP3B." (PMID 37896202, 2023). "In contrast, the upregulation of miR-101-3p via lncRNA NEAT1_2 in hepatocellular carcinoma cells decreased both the mRNA and protein levels of Wee1, inducing tumor radio-sensitization." (PMID 34639030, 2021). "Additionally, BMAL1 and CLOCK can impact the cell cycle of hepatocellular carcinoma cells by regulating the expression of Wee1 and P21, thereby contributing to tumor progression." (PMID 38703241, 2024). "Moreover, DLX6-AS1 interacts with miR-424-5p via the STAT3 signaling pathway, promoting invasion in WEE1-dependent hepatocellular cancer." (PMID 37245177, 2023). "Similarly, lncRNA DLX6-AS1 induces hepatocellular cancer by suppressing apoptosis through the STAT pathway after binding with miR-424-5p in a WEE1-dependent manner." (PMID 37245177, 2023). "The activity of Wee1 was found to be increased in patients with advanced hepatocellular carcinoma when compared with noncancerous liver tissue." (PMID 34639030, 2021).
colon carcinoma (38 papers, 2008 to 2026). "Curcumin inhibited the gene expression of Cdc25c, CDK1, and cyclin B1 and promoted the gene expression of Wee1 in colon cancer cells, causing cell cycle arrest at the G2/M phase." (PMID 33233354, 2020). "Since the Wee1-mediated inhibition of G2-M transition is an essential step after DNA damage, permitting DNA repair prior to entry into mitosis, the decreased expression or loss of the Wee1 gene in colon carcinoma cells suggests its potential role as a tumor suppressor." (PMID 34639030, 2021). "On the other hand, ectopic expression of PER1 was found to inhibit WEE1 expression in human colon cancer cell lines." (PMID 34221066, 2021). "In colon cancer, sulforaphane and curcumin are reported to be able to promote G2/M phase arrest in colon cancer cells by upregulating WEE1 expression, which finally leads to the apoptosis of cancer cells." (PMID 34194536, 2021). "β-Elemene was found to induce the sensitivity of colon cancer cells to VCR by inhibiting WEE1 expression." (PMID 34641334, 2021). "Inhibition of WEE1 by the selective WEE1 inhibitor MK-1775 resulted in anti-tumor effects in several preclinical tumor models including colon cancer, suggesting WEE1 as a potential therapeutic target for anticancer treatment." (PMID 33224881, 2020). "The combination of TIMELESS depletion with Wee1 or CHK1 inhibition demonstrates additive detrimental effects on colon cancer cells." (PMID 30629587, 2019). "In contrast, TIMELESS depletion in combination with Wee1 or CHK1 inhibition further decreased cell metabolic capacity than either perturbation alone in all the colon cancer cell lines tested except for HCT15 cells." (PMID 30629587, 2019). "The Wee1 gene has been reported to be underexpressed in colon cancer and non-small cell lung cancer." (PMID 22839099, 2012). "Of note, inhibition of the Rev1-CT/RIR interaction was synergistic with the ATM and ATR inhibitor VE-821 and the Wee1 inhibitor MK-1775, leading to the formation of daughter strand gaps (DSGs) in replicating DNA, and sensitising bone osteosarcoma and colon cancer cells to these agents." (PMID 35198436, 2021). "Inhibition of Wee1 or CHK1 actually increased the percentage reduction in cell metabolic capacity following TIMELESS depletion suggesting at least additive effects with this combination in all of the colon cancer cell lines tested, but an inhibitory effect in HCECs." (PMID 30629587, 2019). "Similarly, a cDNA array performed on colon carcinoma cell lines and human tissues showed low Wee1 mRNA expression, leading to the speculation that genetic lesions targeting cell cycle regulation occur not only at the G1-S but also the G2-M transition checkpoint during tumor development." (PMID 34639030, 2021). "Additionally, in both mouse colon cancer cell lines (CT26 and MC38), the expression level of WEE1 tended to be higher than that in normal colonic mucosa." (PMID 39335109, 2024). "Therefore, β-elemene could enhance the inhibitory effect of VCR on SW-480 cells, inhibit WEE1 protein expression in a dose and time-dependent manner, enhance the ability of VCR to chemosensitivity of colon cancer cells, and play a pro-apoptotic role." (PMID 34641334, 2021). "Additionally, combination therapy with TIMELESS depletion and either Wee1 or CHK1 inhibition demonstrated at least additive effects in four colon cancer cell lines, but not in HCECs, suggesting this combination may be an efficacious strategy for the treatment of colon cancer." (PMID 30629587, 2019).